RGS12 (regulator of G protein signaling 12)
Diseases named in the same sentence as RGS12 in open-access papers:
RGS12 is named in the same sentence as 46 diseases in open-access papers, as found by Europe PMC text mining. Sharing a sentence is not in itself a finding about the gene and the disease. The quoted sentences say what the papers report.
oral squamous cell carcinoma (5 papers, 2023 to 2024). "Gene knockout assays have shown that RGS12 can inhibit the progression of oral squamous cell carcinoma by controlling the polarization of M1 in TAMs by controlling ciliated MYCBP2/KIF2A signaling." (PMID 38688945, 2024). "Therefore, the results suggest that RGS12 can be used as a potential therapeutic target and prognostic biomarker for oral squamous cell carcinoma." (PMID 38515628, 2024). "In addition, the expression of RGS12 is significantly reduced in oral squamous cell carcinoma (OSCC) tissues, and overexpression of RGS12 represses OSCC cell proliferation and migration through regulating the phosphorylation and SUMOylation of phosphatase and tension homolog (PTEN)." (PMID 37118788, 2023). "RGS12 is an essential suppressor of oral cancer, which binds to phosphatase and tension homolog (PTEN) through the PDZ domain, controls the phosphorylation of PTEN, and further inhibits the AKT/mTOR pathway, thereby inhibiting the occurrence of oral squamous cell carcinoma." (PMID 38515628, 2024).
depression (4 papers, 2021 to 2026). "Changes in the RGS12 gene were associated with both depression and green space exposure." (PMID 42095058, 2026). "RGS12 has been shown to play a role in the pathogenesis of many human diseases, including osteoporosis, fracture repair, arthritis, tumors and cancers (e.g., osteosarcoma, PCa, OSCC), neurological disorders (e.g., anxiety, depression), periodontitis, and hearing disorders." (PMID 40271194, 2025).
schizophrenia (4 papers, 2009 to 2024). A major psychotic disorder characterized by abnormalities in the perception or expression of reality. "An earlier schizophrenia-focused trio study reported identifying a de novo P1120L variant of RGS12 within a male proband diagnosed with depressed-subtype schizoaffective disorder." (PMID 39518985, 2024). "The most promising variants were identified in the gene RGS12, which has been reported in previous next-generation sequencing studies of schizophrenia." (PMID 32066727, 2020). "Independently, we previously identified a non-synonymous de novo variant (R702L) within RGS12 by sequencing the exomes of 53 individuals with sporadic schizophrenia (and the exomes of their non-affected parents)." (PMID 39518985, 2024). "In view of the reported genetic overlap between schizophrenia and BD13, this finding renders RGS12 a highly promising candidate in terms of follow-up analyses." (PMID 32066727, 2020).
bipolar disorder (3 papers, 2024 to 2025). A disorder of the brain that causes unusual shifts in mood, energy, activity levels and the ability to carry out day-to-day tasks. "A recently characterized R59Q reduction-of-function mutation within RGS12 has been associated with familial bipolar disorder, further highlighting its potential relevance to mood and psychostimulant responsiveness." (PMID 41465420, 2025). "RGS12 variants have been considered the most promising candidates in multiple families affected by bipolar disorder identified by WES." (PMID 38606321, 2024). "The interaction of RGS12 with SAPAP3 might affect synaptic stability and signaling, key areas of interest in bipolar disorder research focusing on synaptic homeostasis disruptions as a core element of the disease’s neuropsychiatric manifestations." (PMID 39518985, 2024). "In this way, understanding how the R59Q variation within RGS12, which reduces its PDZ domain’s binding affinity, affects these neurochemical pathways could provide valuable insights into the pathophysiology of bipolar disorder and highlight new therapeutic targets." (PMID 39518985, 2024).
osteosarcoma (3 papers, 2023 to 2025). A usually aggressive malignant bone-forming mesenchymal neoplasm, predominantly affecting adolescents and young adults. "Knockdown of the regulator of G-protein signaling 12 (RGS12) gene expression in osteosarcoma cells prevented YAP phosphorylation and inhibited lung metastasis." (PMID 36632453, 2023). "RGS12 can also act as a tumour suppressor in osteosarcoma by inhibiting the expression and function of other relevant markers of osteosarcoma." (PMID 37924113, 2023). "Thus, RGS12 might suppress osteosarcoma growth by regulating the RhoA/YAP/TEAD1/Ezrin signaling pathway." (PMID 40271194, 2025).
Arthritis (2 papers, 2021 to 2025). Inflammation of a joint. "In related studies, it has been reported that RGS12 regulates the inflammation of arthritis by activating NF-κB to generate a feedback loop." (PMID 34674723, 2021). "Thus, the results to date suggest RGS12 plays a critical role in the pathogenesis of arthritis, including inflammatory arthritis, osteoarthritis, and rheumatoid arthritis, through mediating the dysfunction of macrophages, fibroblasts, and endothelial cells." (PMID 40271194, 2025). "It is possible to modulate arthritis at a fundamental level by targeting RGS12 specifically." (PMID 40271194, 2025).
cardiac hypertrophy (2 papers, 2016 to 2025). "Moreover, marked elevation of RGS12 protein expression was found to associate with pressure-overload cardiac hypertrophy, whereas deletion of Rgs12 was found to decrease cardiomyocyte cross-sectional area, with decreased mRNA levels of common biomarkers of maladaptive cardiac hypertrophy in mice." (PMID 39772618, 2025). "RGS12 is a multi-domain member of the RGS family and plays a regulatory role in various signaling pathways, although the precise effect of RGS12 on cardiac hypertrophy remains largely unknown." (PMID 27690014, 2016).
lung carcinoma (2 papers, 2011 to 2025). "Therefore, it is biologically plausible that RGS4, RGS5, and RGS12 are associated with lung cancer survival." (PMID 21698121, 2011). "Given the differential expression of RGS12 in various tumors and the different effects in different tumors, it can be speculated that RGS12 may also play a role in some other cancers, such as lung cancer." (PMID 40271194, 2025).
Obesity (2 papers, 2024). Accumulation of substantial excess body fat. "Using this criteria RGS2, RGS4, RGS9, and RGS12 were identified as having physiologically relevant transcriptional alterations in obesity compared to lean." (PMID 39142076, 2024). "While the single-cell data set identified RGS2, RGS4, RGS9, and RGS12 as having physiologically relevant transcriptional alterations within EECs in obesity, this finding was only validated for RGS9 in the colon." (PMID 39142076, 2024). "Here, we show in colonic EECs, obesity was associated with an altered RGS profile, with differential expression patterns in colonic RGS2 (underexpression), RGS4 (underexpression), RGS9 (overexpression), and RGS12 (overexpression)." (PMID 39142076, 2024). "RGS12, which was differentially expressed in visceral adipose tissue from morbidly obese patients, and TTC36, which is involved in the occurrence and development of obesity, likely through the immune microenvironment, have both garnered recent attention." (PMID 38550599, 2024). "Colonic expression of RGS2, RGS4, and RGS12 in obesity was not significantly different compared to lean." (PMID 39142076, 2024).
osteoporosis (2 papers, 2019 to 2025). A condition of reduced bone mass, with decreased cortical thickness and a decrease in the number and size of the trabeculae of cancellous bone (but normal chemical composition), resulting in increased fracture incidence. "By targeting RGS12 specifically, it is possible to modulate osteoporosis and inflammation-induced bone loss at a fundamental level." (PMID 40271194, 2025). "Our study also points to a novel role of Rgs12 in OC redox biology, thus forming the molecular basis for developing therapies to modulate ROS for osteoporosis and other diseases of bone loss." (PMID 31490121, 2019). "Here, we comprehensively review the role of RGS12 in human diseases, such as rheumatoid arthritis, osteoporosis, periodontitis, as well as cancers and nervous disorders." (PMID 40271194, 2025).
periodontitis (2 papers, 2022 to 2025). An acute or chronic inflammatory process that affects the tissues that surround and support the teeth. "RGS12 leads to bone erosion through the polarization of macrophages and the release of inflammatory factors through the GPCR and NF-κB pathways and is a potential therapeutic target for chronic periodontitis." (PMID 40271194, 2025).
rheumatoid arthritis (2 papers, 2022 to 2025). A chronic, systemic autoimmune disorder characterized by inflammation in the synovial membranes and articular surfaces. "In a study of rheumatoid arthritis, a significant association was found between RGS12 genetic variation with the response to an immunosuppressive drug." (PMID 35419005, 2022). "Therefore, the PTB domain of RGS12 is a potential therapeutic target for rheumatoid arthritis, while PGE2/EP4 signaling and RGS12/NF-κB signaling form positive feedback for inflammation regulation." (PMID 40271194, 2025).
Anxiety (1 paper, 2025). Intense feelings of nervousness, tension, or panic often arise in response to interpersonal stresses. "Loss of RGS12 is associated with reduced excessive movement at low doses of MDMA, increased brain region-specific SERT expression and 5-HT uptake, and increased anxiety-like and antidepressant-like behaviors." (PMID 40271194, 2025).
Cerebral ischemia (1 paper, 2020). Restriction of arterial blood supply to the brain associated with insufficient oxygenation to support the metabolic requirements of the tissue. "The current findings that cerebral ischemia affects low gamma in free-behaving mouse and that the 30–50 Hz light flickers can restore low gamma to confer neuroprotection through an RGS12-modulated enhancement of CA3-CA1 synaptic plasticity are novel." (PMID 32541656, 2020).
colon cancer (1 paper, 2010). "Our genome-wide strategy to identify immunogenic NMD-resistant transcripts has identified five novel cMS mutations (SFRS12IP1, MED8, ASXL1, FBXL3, RGS12) in at least 45% of eleven MSI-High colon cancer cell lines tested." (PMID 21209843, 2010).
Duchenne muscular dystrophy (1 paper, 2019). Duchenne muscular dystrophy (DMD) is a neuromuscular disease characterized by rapidly progressive muscle weakness and wasting due to degeneration of skeletal, smooth and cardiac muscle. "When tissue-restricted Rgs12 loss was cross-bred into the mdx mouse model of Duchenne muscular dystrophy, no change in the dystrophic phenotype was observed over time." (PMID 31408461, 2019). "However, when mice lacking skeletal muscle expression of Rgs12 were cross-bred with mdx mice (a model of human Duchenne muscular dystrophy), no increase in muscle degeneration was observed over time." (PMID 31408461, 2019).
female infertility (1 paper, 2024). Diminished or absent ability of a female to achieve conception. "We have identified an RGS12 variant as the potential cause of female infertility characterized by arrest at the PN stage during multiple IVF and ICSI." (PMID 38606321, 2024).
glomerulosclerosis (1 paper, 2022). A hardening of the kidney glomerulus caused by scarring of the blood vessels. "Furthermore, serum RGS12 ICx exhibited a positive correlation with chronicity index (CI), as well as glomerulosclerosis, fibrous crescents, tubular atrophy, and interstitial fibrosis." (PMID 35419005, 2022).
Infertility (1 paper, 2024). "Therefore, our findings will facilitate genetic diagnoses for RGS12 mutation in identifying patients with infertility who are undergoing IVF and ICSI." (PMID 38606321, 2024). "A variant in RGS12 extends the genetic causes of infertility." (PMID 38606321, 2024).
liver disease (1 paper, 2022). "ROC curve was used for joint diagnosis of hsa_circ_0006091 and AFP/RGS12, respectively in HCC s (n = 52) versus adjacent tissues s (n = 52), HCC versus benign liver disease tissues (n = 12)." (PMID 35068348, 2022).
muscular dystrophies (1 paper, 2019). "Our hope is that future findings as to the role(s) of RGS12 in muscle repair and muscle wasting could inform novel therapeutic strategies for DMD and other muscular dystrophies." (PMID 31408461, 2019).
oral cancer (1 paper, 2023). "Here, we found that loss of RGS12 in macrophages promotes oral cancer proliferation and invasion in the early stage." (PMID 36797232, 2023). "Interestingly, loss of RGS12 inhibits the expression of M1 macrophage (CD86) but promotes the expression of M2 macrophage (CD163) in 8-week 4NQO-induced oral cancer tissues." (PMID 36797232, 2023). "In this study, by investigating the roles of RGS12 on TAMs from mice with oral cancer, we revealed that RGS12 is an essential factor to control immune activation in oral cancer by regulating macrophage polarization and ciliogenesis via MYCBP2/KIF2A." (PMID 36797232, 2023). "Here, transcriptome profiling analysis of human oral cancer tissues indicated that regulator of G protein signaling 12 (RGS12) regulates pathologic processes and immune-related pathways." (PMID 36797232, 2023). "To further characterize the function of RGS12 in vitro, we stably overexpressed RGS12 in primary TAMs isolated from oral cancer tissues of wild-type (WT) mice." (PMID 36797232, 2023). "Our results demonstrate that RGS12 is an essential oral cancer biomarker and regulator for immunosuppressive TAMs activation." (PMID 36797232, 2023). "We then confirmed that the RGS12 expression was significantly downregulated in human oral cancer samples by immunohistochemistry analysis." (PMID 36797232, 2023). "Mice with RGS12 knockout in macrophages displayed decreased M1 TAMs in oral cancer tissues, and extensive proliferation and invasion of oral cancer cells." (PMID 36797232, 2023). "As expected, RGS12 expression was significantly reduced in F4/80+ macrophages from the 16-week 4NQO-induced oral cancer tissues in comparison with that from 8-week 4NQO-induced oral cancer tissues." (PMID 36797232, 2023). "However, downregulation of RGS12 in oral cancer inhibits the MYCBP2 activity, which further causes decreased ciliogenesis, increased M2 TAMs polarization, and promotes oral cancer growth." (PMID 36797232, 2023). "Given that macrophage RGS12 is important for oral cancer development, targeting the RGS12/MYCBP2 pathway may be an attractive therapeutic avenue in this disease." (PMID 36797232, 2023). "Interestingly, Kaplan-Meier survival analysis indicated that the RGS12 levels in oral cancer were significantly correlated with the survival rate." (PMID 36797232, 2023). "Upregulation of RGS12 activates phosphorylation of MYCBP2 to enhance ciliogenesis by degrading KIF2A and promotes the M1 TAMs polarization to further eliminate oral cancer cells." (PMID 36797232, 2023).
osteopetrosis (1 paper, 2022). Osteopetrosis, also known as marble bone disease, is a descriptive term that refers to a group of rare, heritable disorders of the skeleton characterized by increased bone density on radiographs. "Compared to RGS10, conditional knockout of RGS12 in osteoclast lineage (CD11b-Cre and Mx1-Cre) also caused osteopetrosis phenotype." (PMID 35573989, 2022). "Different from RGS4, the deletion of RGS10 or RGS12 in osteoclasts causes osteopetrosis phenotype through controlling the calcium oscillations and oxidative stress mediated Nrf2/Keap1 signaling pathways in mice, indicating their positive regulation in aging mediated osteoporosis." (PMID 35573989, 2022).
psoriasis (1 paper, 2024). An autoimmune condition characterized by red, well-delineated plaques with silvery scales that are usually on the extensor surfaces and scalp. "Among the 2 shared SNPs between LDL and psoriasis, rs28484982 was near RGS12, a gene that exhibited differential expression in visceral adipose tissue from morbidly obese patients." (PMID 38550599, 2024).
tumor (7 papers, 2019 to 2025). "RGS12 enhances the phosphorylation of Myc-binding protein 2 (MYCBP2) to degrade the ciliary protein KIF2A and cilia disassembly, which promotes tumor-associated macrophage polarization into M2 macrophages." (PMID 40271194, 2025). "Collectively, these findings indicate that RGS12 acts as a tumour suppressor and a novel promising target for the treatment of various cancers." (PMID 37924113, 2023). "RGS12 is involved in regulating a variety of important transmissions in the body, which is important for normal as well as tumour tissues and cells." (PMID 37924113, 2023). "Wang et al146 identified a putative tumor suppressor in AA men, RGS12, that influences apoptosis by reducing MNX1 and AKT levels." (PMID 33599076, 2021). "Targeting RGS12 may provide a new strategy for anti-tumor therapy." (PMID 40271194, 2025). "Thus, RGS12 is an essential tumor suppressor and might be a potential therapeutic target for OSCC." (PMID 40271194, 2025). "Of these, DHRS3, DUSP4, GAN, RGS12, and TRIM14 are known oncogenes or tumor suppressors (as indicated by CancerMine)." (PMID 33849068, 2021). "The CXCR2-ADRA1A function module generated from our data included several immune-related genes, such as CXCL5, CXCL13, RGS12, and CXCR1, indicating that the DNA methylation function module might involve in the immune response regulation in the tumor microenvironment of sMPLC." (PMID 36611170, 2023).
cancer (6 papers, 2017 to 2025). A tumor composed of atypical neoplastic, often pleomorphic cells that invade other tissues. "GO and KEGG analyses were used for the evaluation of various genes, such as QKI, EGFR, and RGS12 that are closely associated with the incidence of cancer." (PMID 35068348, 2022). "Notably, genomic clusters of viral integrations were identified in TERT (number of integration sites within a genomic cluster (NGC) of 6), KMT2B (NGC = 4)—which was recently identified to be a likely cancer driver gene—and RGS12 (NGC = 3)." (PMID 32025001, 2020). "The other three genes that showed consistent expression across all models, SORBS2, RGS12, and EXOC6, have been investigated as predictive or prognostic cancer biomarkers." (PMID 28798985, 2017). "We used GO and KEGG analysis to analyze many cancer-related genes, including QKI, CTNNA1, GSK-3b, and RGS12, which had not been previously identified in HCC." (PMID 35068348, 2022).
cardiac disease (1 paper, 2019). "We speculate that the ability of Rgs12 to regulate Nrf2 could be an important clue to better understand the role of Rgs12 in the context of cardiac disease and tumorigenesis, in which ROS is known to have significant implications." (PMID 31490121, 2019).
RGS12 also shares sentences with these, for which no sentence is quoted: attention deficit-hyperactivity disorder (1 paper); bacterial infection (1); Buruli ulcer (1); carcinoma in situ (1); dysplasia (1); frontotemporal dementia (1); glioblastoma (1); head and neck cancer (1); hearing disorder (1); hepatocellular carcinoma (1); inflammation (1); myeloma (1); neurological disorders (1); osteoarthritis (1); periodontal disease (1); prostate carcinoma (1); rheumatic diseases (1); tuberculosis (1); Wolfram syndrome (1).